LEP (leptin)
Diseases named in the same sentence as LEP in open-access papers (continued):
Sharing a sentence is not in itself a finding about the gene and the disease.
cholelithiasis (8 papers, 2017 to 2024). The presence of crystallized deposits forming in the gallbladder or biliary tree, primarily composed of cholesterol, bilirubin, and bile. "The changes in the mRNA expression of leptin and leptin receptor within the gallbladder of dogs with cholelithiasis further underline that leptin may be a factor involved in the development of cholelithiasis, considering its important physiological role in gallbladder." (PMID 29088261, 2017). "Certain research has revealed a notable difference in serum leptin levels between patients with cholelithiasis and healthy individuals." (PMID 39427492, 2024). "At present, most of the pathophysiological mechanisms of cholelithiasis in patients with high BMI are considered to be related to leptin." (PMID 39427492, 2024). "In another in vitro experiment it was also demonstrated that leptin affects cholelithiasis formation by modulating bile acid metabolism." (PMID 37964952, 2023). "In this study, we aimed to examine serum leptin concentrations and serum biochemical parameters in patients with GBM or cholelithiasis before and after surgery and investigated changes in leptin concentrations over time." (PMID 31238989, 2019). "Our pre- and postoperative short-term follow-up study revealed that serum leptin concentrations were associated with the severity of disease and clinical signs both before and after surgery in dogs with GBM and cholelithiasis." (PMID 31238989, 2019). "Another study in humans showed that the serum leptin concentrations in patients with cholelithiasis were higher than those in controls." (PMID 29088261, 2017). "In cholelithiasis patients who underwent cholecystectomy, serum leptin levels were significantly higher than in patients that had not undergone surgery (p < 0.001)." (PMID 29088261, 2017). "In this study, we determined that both serum cholesterol and triglyceride levels positively correlate with leptin levels in both healthy and cholelithiasis patients." (PMID 29088261, 2017). "Leptin and leptin receptor expression was upregulated in the gallbladder tissues of cholelithiasis patients (p < 0.01 and p < 0.001, respectively)." (PMID 29088261, 2017). "This study showed that the serum leptin concentrations in dogs with cholelithiasis were significantly higher than those in healthy dogs." (PMID 29088261, 2017). "In dogs with cholelithiasis, serum concentrations of leptin (p < 0.001), total cholesterol (p < 0.001), and triglycerides (p < 0.001) were significantly higher compared with those in healthy dogs." (PMID 29088261, 2017). "In the cholelithiasis group, serum leptin concentrations were significantly higher than those in the healthy group (p < 0.001)." (PMID 29088261, 2017). "Although previous studies performed in both humans and animals revealed multiple roles of leptin in various organs, little information is available regarding the correlation between leptin and cholelithiasis in dogs." (PMID 29088261, 2017). "We also demonstrated a relative increase in leptin and leptin receptor mRNA expression in the gallbladder tissues of dogs with cholelithiasis compared with that in healthy dogs." (PMID 29088261, 2017). "The mRNA expression levels of leptin and its receptor were significantly upregulated in dogs with cholelithiasis, compared with those in the healthy control dogs (p < 0.01 and p < 0.001, respectively)." (PMID 29088261, 2017). "Furthermore, leptin-mediated AMPKα2 regulated bile acid metabolism, thereby affecting cholelithiasis, especially the formation of primary intrahepatic bile duct stones." (PMID 37641009, 2023). "Furthermore, the expression levels of leptin and its receptor are increased in the gallbladder in canine patients with GBM and cholelithiasis, and serum leptin concentrations are also significantly increased compared with those in normal healthy dogs." (PMID 31238989, 2019).
cholelithiasis (continued). "Positive correlations were observed between serum leptin and total cholesterol (95% confidence interval (CI) = 0.61–0.89, r = 0.725, p < 0.001), and between leptin and triglycerides (95% CI = 0.63–0.89, r = 0.782, p < 0.001) in the cholelithiasis group." (PMID 29088261, 2017). "In addition, tissue concentrations of leptin and its receptor were measured in the gallbladder using real-time polymerase chain reaction (PCR) in dogs with cholelithiasis and healthy dogs." (PMID 29088261, 2017). "Moreover, the reduced phosphorylation level of AMPKα2 was observed in gallbladder stones and primary intrahepatic bile duct stones, and leptin-mediated AMPKα2 could affect cholelithiasis by regulating bile acid metabolism." (PMID 37641009, 2023). "The occurrence of GBM and cholelithiasis is related to various pathophysiological factors, including gallbladder motility, biliary excretion, and changes in biliary properties, and several previous studies on the direct or indirect relationships between these factors and leptin have been reported." (PMID 31238989, 2019). "Based on these results, we can hypothesize that the upregulation of the expression of leptin and its receptor in the gallbladder of cholelithiasis patients is a response aimed at maintaining the homeostasis of gallbladder motility and bile composition under pathological conditions." (PMID 29088261, 2017). "Therefore, our results further suggest that serum leptin levels may represent an additional useful biomarker for the assessment of the severity of cholelithiasis in dogs." (PMID 29088261, 2017). "In this study, we performed pre- and postoperative short-term follow-up analyses to confirm changes in serum leptin levels before and after cholecystectomy due to gallbladder mucocele (GBM) or cholelithiasis in dogs." (PMID 31238989, 2019). "Taken together with the results of previous studies, our findings supported the possibility that serum leptin levels may have applications in assessing the prognosis of canine patients undergoing surgery for GBM and cholelithiasis." (PMID 31238989, 2019). "In addition, our findings confirmed the potential application of serum leptin levels as a parameter to assess the severity of GBM and cholelithiasis before surgery." (PMID 31238989, 2019). "However, further studies including larger cohorts are required to definitively elucidate the relationship between leptin and gallbladder diseases, such as GBM and cholelithiasis, in dogs." (PMID 31238989, 2019). "The results of this study showed that serum leptin concentrations were not significantly correlated with age, sex, breed, body weight, or BCS in either dogs with cholelithiasis or healthy dogs." (PMID 29088261, 2017).
gout (8 papers, 2012 to 2024). A condition characterized by painful swelling of the joints, which is caused by deposition of urate crystals. "High concentrations of leptin were detected in both severe gout patients and in the acute phase of gout." (PMID 35268067, 2022). "We also attempted to investigate the causal effects of leptin on UA and gout, but there were not enough SNPs as IVs to support MR analyses." (PMID 35268067, 2022). "The role of BMI in gout pathogenesis could be elucidated based on how leptin responds to inflammation related to monosodium urate crystals." (PMID 33858492, 2021). "In a study comprising 258 male gout patients and 111 males undergoing annual check-ups, elevated levels of leptin and plasminogen activator inhibitor-1, coupled with reduced ADPN and ADPN/leptin ratio, were noted in patients with gout (p < 0.05, respectively)." (PMID 38464719, 2024). "After performing a linear correlation of the Leptin and AdipoQ values, there was no important correlation (r > 0.5) between other metabolic variables and those measuring the activity of gout." (PMID 26131838, 2015).
iron deficiency (8 papers, 2018 to 2026). "Leptin levels are low in TB patients at nutritional risk, so weight loss is significant in TB patients with nutritional disorders." (PMID 36506012, 2022). "Moreover, iron deficiency is known to influence appetite-regulating hormones such as ghrelin and leptin, contributing to reduced food intake and further nutritional compromise." (PMID 41036189, 2025). "Leptin thus lies at the crossroad between neurological, metabolic and nutritional disorders that may arise from societal changes in lifestyle, stress level and eating behaviors." (PMID 30106375, 2018).
kidney cancer (8 papers, 2020 to 2025). Primary or metastatic malignant neoplasm involving the kidney. "Interestingly, rs12145690 has been observed in a Spanish Mediterranean female population associated with circulating leptin levels, adjusted for BMI, and rs970467 has been associated with lipid markers related to kidney cancer." (PMID 35741707, 2022). "Correlation between adiponectin and leptin with clinical and pathological characteristics of patients with kidney cancer." (PMID 41255618, 2025). "Leptin was higher in the conditioned media of human adipose explants from kidney cancer tissue, and the incubation with RCC cell lines appeared to decrease cancer cell adhesion and increase cell migration." (PMID 33804101, 2021). "In experimental models, in the Renca murine kidney cancer line, leptin increases invasiveness in a manner dependent on ERK1/2 kinase and Rho GTPase." (PMID 33334030, 2020). "Furthermore, data from public databases indicate leptin RNA expression in a broad range of cancer types, including kidney cancer." (PMID 33804101, 2021). "The relationship between leptin and kidney cancer has been little explored." (PMID 33334030, 2020).
lymphoma (8 papers, 2017 to 2025). A malignant (clonal) proliferation of B- lymphocytes or T- lymphocytes which involves the lymph nodes, bone marrow and/or extranodal sites. "For example, little information, if any, was provided for the leptin levels in each patient, hence the role of leptin deficiency in lymphoma development cannot be fully explored here." (PMID 40469440, 2025). "Our study showed that during early surveillance, the adiposity, HOMA-IR index, concentration of leptin, and leptin/adiponectin ratio are strongly associated with MS development in children surviving lymphoma and ALL." (PMID 28193268, 2017). "However, leptin therapy has been associated with the development of lymphoma." (PMID 30923630, 2019). "To explore the physiological significance of the p73γ-Leptin pathway, we found that Leptin expression correlates well with isoform switch from p73α to p73γ in a set of dog lymphomas." (PMID 37650871, 2023). "Considering that the p73γ is highly expressed in tumors such as dog lymphoma, it is possible that p73γ plays a critical role in activating the Leptin signaling pathway in tumors, which subsequently promotes tumorigenesis." (PMID 37650871, 2023). "(H) The levels of p73γ, Leptin, and actin were examined in 3 normal dog lymph nodes and 16 dog lymphomas." (PMID 37650871, 2023). "Those notions are especially significant since NF-kB, STAT3, PI3K, and AKT pathways are activated in lymphoma cells via leptin/LEPR signaling and improving bcl-2 expression." (PMID 36555171, 2022). "Furthermore, we showed that p73α-γ switch is detected in a subset of dog lymphomas, along with elevated expression of Leptin." (PMID 37650871, 2023). "Similarly, Leptin and p73γ transcripts were found to be highly expressed coordinately in dog lymphomas compared to normal dog lymph nodes (Leptin and p73γ panels, compare lanes 1–3 with 4–19)." (PMID 37650871, 2023). "Several studies have analyzed the role of leptin genes in lymphomas." (PMID 36555171, 2022). "Specifically, leptin signaling pathways can promote lymphomas." (PMID 36555171, 2022). "Furthermore, to our knowledge, there are no formal scientific studies that demonstrate increased lymphoma risk in leptin-deficient states, including non-AGL lipodystrophy syndromes and CLD." (PMID 40469440, 2025). "Hence, our analysis does not provide supporting evidence for an association between leptin deficiency and lymphoma development." (PMID 40469440, 2025). "Similar to leptin genes, the relationship between the concentration of circulating leptin or LEPR expression and lymphomas has also been studied." (PMID 36555171, 2022). "Leptin levels were not routinely reported for the patients included in the FAS, and only one patient each with CLD and suspected CGL had lymphomas (Patients 15 and 16) were identified in our analysis (n=2/17, 12% of lymphomas)." (PMID 40469440, 2025).
male infertility (8 papers, 2007 to 2025). The inability of the male to effect fertilization of an ovum after a specified period of unprotected intercourse. "The mechanistic basis for the regulatory role of LEP signaling in male infertility, especially between LEPR polymorphisms of spermatozoa and male infertility, awaits further analysis." (PMID 37662867, 2023). "In light of progress in research on reproductive physiology, studies have shown that leptin is inextricably linked with reproduction, especially in male infertility." (PMID 36213199, 2022). "Further study is needed to explore the mechanism of how leptin is potentially associated with male infertility." (PMID 36213199, 2022). "It is the first meta-analysis of the relationship between serum or seminal leptin concentration and the risk for male infertility." (PMID 36213199, 2022). "This study indicated that serum or seminal leptin was statistically associated with male infertility." (PMID 36213199, 2022). "Considering the sporadic prior research, we used the updated meta-analysis to investigate the relationship between leptin concentration and the association of male fertility dysfunction, and we aimed to provide new clues for the etiology of male infertility." (PMID 36213199, 2022). "The rs10244329 polymorphism in the LEP gene showed a statistically significant difference in fertility; it appeared that variability in the LEP gene might be associated with male infertility." (PMID 37662867, 2023). "This study suggests that serum and tissue leptin are associated with male infertility." (PMID 36213199, 2022). "Leptin plays a potential role in association with male infertility." (PMID 36213199, 2022). "Notably, considering progress in research on reproductive physiology, studies have shown that leptin is inextricably linked with reproduction, especially in male infertility." (PMID 36213199, 2022). "This study may effectively reveal the relationship between leptin together with other hormones and its association with male infertility." (PMID 36213199, 2022). "Also, the male infertility, seen in the leptin-deficient ob/ob mice that are on a C57BL/6 background, is rescued when the deficiency is bred into the BALB/c strain." (PMID 17241468, 2007). "Through peripheral blood samples for DNA extraction and genotypic analysis, the association between polymorphisms of LEP and LEPR genes and male infertility has been examined." (PMID 37662867, 2023). "Previous study showed that leptin administration in adult rat lead to upregulation of serum FSH and LH, implying that leptin can possibly affect male infertility by hormone profile modulation." (PMID 32993674, 2020). "In this study, both seminal and serum leptin were increased and correlated with male infertility." (PMID 36213199, 2022). "The findings regarding the secretion of leptin from human spermatozoa accompanied by the presence of leptin receptors on human spermatozoa and in seminal plasma may open a novel field of study in male infertility." (PMID 36213199, 2022). "One of the next perspectives is to determine the concentrations of leptin and other hormones in the issue of male infertility and the mechanisms that could be involved, since their potential effect on male reproduction is highly dependent on metabolic cooperation between testicular cells." (PMID 40566611, 2025).
metastatic tumors (8 papers, 2010 to 2020). "Higher OB-Rb and leptin expression levels were found in ascites and metastatic tumors, particularly in overweight patients." (PMID 26053184, 2015). "In addition, we detected increased expression of MMP-13 in the metastatic tumors overexpressing leptin, suggesting an important role of MMP-13 in leptin-induced cancer progression." (PMID 25948792, 2015). "HIF-1α in primary and metastatic tumors without preoperative therapy positively correlated with leptin (p < 0.0001, r = 0.532; p = 0.013, r = 0.533, respectively) and ObR (p = 0.002, r = 0.319; p = 0.083, r = 0.387, respectively)." (PMID 20569445, 2010).
Myocardial fibrosis (8 papers, 2016 to 2025). "In our study, we demonstrated relationships between tEAT and levels of pro-inflammatory cytokines (TNF-α and IL-6), adipokines (leptin and adiponectin), and markers of myocardial fibrosis (MMP-3, TGF-β, and collagen)." (PMID 34088886, 2021). "Concomitant IR and overexpression of cardiac leptin led to cardiomyocyte hypertrophy, myocardial fibrosis, increased macrophage infiltration, and augmented capillary density as revealed on POD-30." (PMID 30312306, 2018). "Furthermore, leptin influences myocardial remodeling by stimulating myocardial fibrosis, further contributing to the development of HF." (PMID 40417460, 2025).
pancreatitis (8 papers, 2012 to 2025). Inflammation of the pancreas. "One study reported that in pancreatitis induced by cerulean injection in lean rats, serum leptin concentration was increased." (PMID 23285260, 2012). "In rats with caerulein-induced pancreatitis, leptin administration (1 or 10 μg/kg BW, i." (PMID 33935782, 2021). "In the same pancreatitis model, leptin administration (10 μg/kg BW, i." (PMID 33935782, 2021). "Intriguingly, the pancreas could secrete leptin and its protective role in pancreatitis has been described." (PMID 31091785, 2019). "Several in vivo studies have reported that leptin may exert a protective effect on pancreatitis." (PMID 33935782, 2021). "Similarly, leptin dysregulation seems to be involved in the pancreatitis pathophysiology." (PMID 31091785, 2019).